MYC (MYC proto-oncogene, bHLH transcription factor)
Diseases named in the same sentence as MYC in open-access papers (continued):
Sharing a sentence is not in itself a finding about the gene and the disease.
cancer (continued). "MYC and MCL1 mRNA downregulation has been described previously from the blood of patients treated with enitociclib during dose escalation and across many cancer indications including NHL and solid tumors using a qPCR clinical trial assay." (PMID 37882668, 2023). "This increase was shown to be partly due to copy-number gains of the MYC locus originating from parental cancer cells but not from parental macrophages by immunoFISH assays." (PMID 37848444, 2023). "While MYC is a well-known oncogenic transcription factor and a major driver for a wide variety of cancers, no effective drugs that directly target MYC are currently available." (PMID 37049806, 2023). "However, in MYC-transformed cells, activated MYC promotes DSB repair in response to DNA damage, enabling cancer cell survival." (PMID 37755397, 2023). "MYC, a multifunctional transcription factor protein, behaved as a common gene signature upregulated by IKZF1 N159Y/S,25, 34 and contributed to the pathogenesis of various types of human cancers through different mechanisms." (PMID 37345307, 2023). "On the other hand, PAMcluster-C, which had the worst survival probability, had a variety of immunosuppressive cell infiltration, including MDSC, Tregs, mast cells, and significantly activated cancer-related pathways such as WNT, NOTCH, and MYC pathways, which was consistent with previous studies." (PMID 37202800, 2023). "They activate cancer cell signaling pathways and transcription factors, including IGF1/α6β4 complex, FGFR2, TIMP, DNA replication and mTOR signaling, Smad7, KLF4, and TBX2, and downstream proto-oncogenes such as MYC, MET, and CDK1, which facilitate cancer progression." (PMID 37046676, 2023). "c-MYC regulates gene expression through MAX and is an overactive gene in cancer cells." (PMID 37204526, 2023). "Such cooperation is also observed for HIF2α, although unlike HIF1α, HIF2α is better known to promote MYC activity in cancer." (PMID 37601651, 2023). "Cancer cell lines harboring MYC amplification versus lines with normal MYC copy numbers displayed significantly elevated area under the dose–response curve (AUC) values for multiple mTORi." (PMID 37642941, 2023). "And while we observe some anti-cancer effects of PLK1is as single agents in MYC-non-amplified background, it is less significant compared to MYC-amplified cells, possibly due to moderate expression of and dependence on of MYC and/or PLK1." (PMID 37183219, 2023). "In UCEC, the same infiltration pattern was observed among samples harboring mutations of genes regulating DNA damage repair and cell cycle but not in patients with mutations of classical cancer hallmarks such as PTEN, MYC, KRAS, BAX and ect." (PMID 37917664, 2023). "Moreover, MBZ can modulate various cancer-associated pathways, including MAPK14, MEK-ERK, C-MYC, USP5/c-Maf, TNIK, XIAP, ELK/SRF, NFKB, MYC/MAX, E2F/DP1, TGF/SMAD, AP1, and STAT1/2, dependent on the specific cancer model." (PMID 36674870, 2023). "However, we found that c-MYC S405A cancer cells had lower c-MYC, cyclin D1, and CDK4 expression than c-MYC WT cancer cells, while c-MYC S405E cancer cells had higher c-MYC, cyclin D1, and CDK4 expression than c-MYC WT cancer cells." (PMID 37596667, 2023). "RT-qPCR analysis and western blotting revealed that 1 and 2 suppressed the expression of c-MYC and k-RAS genes at mRNA and protein levels in HCT116 human cancer cells in a dose-dependent manner, with 2 being more efficient, although both metallohelices were applied at equitoxic concentrations." (PMID 37019444, 2023). "However, c-MYC and/or HER2 are important genetic cancer drivers, and the success of future therapeutic efforts will likely require novel drug development as well as the assessment of drug combinations." (PMID 35448150, 2022).
cancer (continued). "Furthermore, soluble factors derived from CH-hMSCs and PL-hMSCs also increased the expression levels of MYC, SNAI1, and TWIST, which play critical roles in the epithelial-mesenchymal transition and migration of cancer cells." (PMID 36406002, 2022). "Besides its role in cellular proliferation, MYC has been recognized as regulating epithelial-to-mesenchymal (EMT) transition and in the general acquisition of invasive properties of cancer cells." (PMID 35354467, 2022). "Cancer cells possess greater MYC dependence than normal cells, but it is not clear how MYC regulates cancer transition." (PMID 35267409, 2022). "MYC-NICK, a cytoplasmic proteolytic product of MYC that lacks the DNA binding domain and thus, is unable to regulate gene transcription, was also shown to play a pro-survival role in cancer cells." (PMID 35159381, 2022). "Previous studies had shown that cancer stem cells maintain their stem cell-like biological characteristics through a high expression of specific stemness markers (such as SOX2, CD44, CD133, and MYC)." (PMID 35859724, 2022). "Paradoxically, we identify a critical function of EZH2 in human cancers is to stabilize MYC-family oncoproteins and sustain MYC(N) dependent transcriptional amplification independent of its methyltransferase activity." (PMID 35013218, 2022). "The cancer-specific 8q21.3-q24.3 amplifications in ccRCC cells therefore co-opt a lineage-factor-dependent physiological programme that supports MYC expression and proliferation that is already present in normal renal epithelial cells." (PMID 35676472, 2022). "It is well known that the deregulation of the ubiquitin-proteasome pathway is critical for c-MYC protein accumulation in cancers where no c-MYC amplification is observed." (PMID 36230763, 2022). "Overall, these findings highlight a novel role for Survivin in mediating the cooperative actions of KRAS and MYC during malignant transformation and raise the possibility that targeting Survivin may offer therapeutic benefits against KRAS-driven cancers." (PMID 36581205, 2022). "It would be interesting to investigate whether the mechanism of resistance to PRMT5-targeted therapies mediated by the oncogenic axis, MSI2/c-MYC/BCL-2, could be extrapolated to the other cancers." (PMID 36167829, 2022). "Unconstrained growth in MYC- and MYCN-driven cancers is thus dependent on metabolic pathways, which may serve as novel targets for cancer therapy." (PMID 35943801, 2022). "We first determined the effect of MB2 residue substitution and S146L on MYC:TRRAP binding, postulating that due to the proximity of this residue to MB2 and its recurrence in cancer, it may induce a gain-of-function by modifying TRRAP binding to MYC." (PMID 36018850, 2022). "Finally, using the Cistrome Data Browser, we also found that c-MYC bound and regulated the expression of CXCR4 in several different human cancer cell lines." (PMID 35853880, 2022). "An example of this observation is given by the MYC oncogene, where SE were found near the MYC gene locus in multiple cancer cell-types, but not in their related normal cells." (PMID 35053311, 2022). "While in some situations this increased expression of MTBP may be due to the high proliferative state in these cancers and/or MYC dysregulation, the MTBP gene undergoes amplification in multiple cancers." (PMID 35741402, 2022). "Using qPCR assay for known genes modulated NT157 in other cancer models, we identified that NT157 decreased expression of oncogenes BCL2, CCND1, MYB, and MYC and increased genes related to cellular stress and apoptosis, JUN, BBC3, CDKN1A, CDKN1B, FOS, and EGR1 (all p < 0.05)." (PMID 36224313, 2022). "However, only a few of these genes have been extensively studied for cancer treatment, including KARS, MYC, EGFR, FGFR, BRAF, PLK1, EphA2." (PMID 36015212, 2022).
cancer (continued). "While downregulation of c-MYC and G2/M checkpoint genes explains the antiproliferative activity, downregulation of TGF-beta and WNT/Beta-catenin pathways suggest the suppression of cancer cells stemness and metastasis." (PMID 36079576, 2022). "This would be highly significant because reducing MYC activity or expression has been shown to have a therapeutic benefit in several different forms of cancer and even in cancers not driven by MYC itself." (PMID 35741402, 2022). "Furthermore, oxidative phosphorylation, MYC targets, E2F targets, and androgen response were also closely related to the expression of SPA17 in cancers." (PMID 35592314, 2022). "Furthermore, it has been also observed that MYC, an essential TF for regulating EMT and/or cancer stem cells, showed increased expression." (PMID 36362083, 2022). "Our patient's cancer did have an MYC rearrangement but not BCL2 or BCL6 rearrangements, and cells displayed both mature and immature markers, making HGBL, NOS a possible diagnosis." (PMID 36158446, 2022). "Therefore, BET inhibition has been effective in preclinical studies of multiple cancer types, especially for many hematopoietic system cancers that rely on constant BRD4 activity to express MYC." (PMID 35303910, 2022). "Since c-MYC has a significant impact on cell fate, it is not surprising that cancer cells have evolved sophisticated methods for ensuring that it maintains proper expression levels." (PMID 36230763, 2022). "The amount of Let-7 decreases with T-cell activation, c-MYC is suppressed, and energy metabolism switches from OXPHOS to glycolysis, leading to an appropriate CTL response to virus-infected cells or cells presenting cancer antigens." (PMID 36483029, 2022). "Our work extends the previous studies by showing the regulation of splicing factors and functionally coordinated embryonic splicing events by MYC, BRD, FOX family of TFs in the developmental context, thus providing further mechanistic links between development and cancer." (PMID 36509773, 2022). "Furthermore, the MTA3 expression levels were correlated with cancer hallmarks, including the G2/M checkpoint, E2F1 targets, and MYC targets." (PMID 36050478, 2022). "Other groups also elucidated that MYC inhibitors and HDAC inhibitors, such as SAHA, may have cross effects to fight against cancers." (PMID 35591851, 2022). "Furthermore, pharmacological inhibition of ATR reversed TNBC cell resistance to topotecan, whereas MYC knockdown and JNK inhibition reduced cancer cell sensitivity." (PMID 35844787, 2022). "Moreover, c-MYC and CCND1 are markers of cancer cell proliferation and cell cycle progression, and western blotting showed that the expression of c-MYC and CCND1 was higher in the MED16 overexpression group." (PMID 36294896, 2022). "Like its physiological counterpart, oncogenic MYC promotes energy production and anabolic pathways, but does so unceasingly, regardless of external growth signals, to sustain cancer hyperproliferation." (PMID 36214609, 2022). "The MYC gene resides within a ~3 Mb gene-poor locus which encompasses multiple domains proximal or distal to its TSS sharing epigenomic and functional characteristics of cis-acting elements, such as enhancers and SEs, defined in distinct cancer types." (PMID 36139535, 2022). "Another important pathway frequently altered in cancer cells is the one regulating the YAP/TAZ transcriptional coactivators, which promote the expression of genes sustaining aerobic glycolysis (such as WNT, MYC, HIF-1), EMT, and drug resistance." (PMID 35626081, 2022). "Furthermore, MYC, mTOR, and HIF-1 are the main mediators regulating SLC transporters and glutamine synthase relative enzymes in cancers." (PMID 36052242, 2022). "MYC can recruit epigenetic modifiers, such as the histone acetyltransferases p300/CBP or the histone deacetylases (HDACs) HDAC1 and HDAC3 to activate or repress distinct genes in cancer cells." (PMID 36068335, 2022).
cancer (continued). "Notably, many studies have shown that MYC overexpression drives the progression and metastasis of many cancer types including PC12–17, and that MYC knockdown substantially inhibits the metastasis of PC and other cancers." (PMID 35115556, 2022). "Similarly, SCLC in the chemo-refractory group was enriched in cell proliferation-related gene sets, including E2F targets, G2M checkpoint, MYC targets v1 and MTORC1 signaling, as well as cancer stemness-related gene sets, Wnt beta-catenin signaling." (PMID 36428585, 2022). "The oncogene MYC has been shown to upregulate lactate dehydrogenase A (LDHA), an important glycolytic enzyme that is necessary to increase the glycolytic rate and tumorigenic potential of cancer cells." (PMID 35530337, 2022). "The potential mechanism of cancer cells could be due to the activation of oncogenes (RAS and MYC protein) that lead to the overexpression of growth factors that stimulate the expression of cyclin-dependent kinase/cyclin D protein." (PMID 36145353, 2022). "In addition, m6A modification also regulates multiple signaling pathways, including the AKT, MYC, NF-κB and YAP pathways, to promote cancer growth 30-32." (PMID 35399719, 2022). "Hypotheses behind the benefits of statins in cancer include downregulation of EMT markers, a decline in MYC expression, and preferential action against “stem-like” subpopulations." (PMID 35624221, 2022). "Considering it is estimated that over 40% of cancers overexpress MYC, it may be beneficial to target HIF-1α and MYC using overlapping pathways and direct or indirect HIF-2α targets." (PMID 35267567, 2022). "Interestingly, even at the level of cancer patient survival, the observation that MTBP is a limiting factor for MYC oncogenic activity can be observed." (PMID 35741402, 2022). "In cancer, FBXW7 can inhibit macrophage M2-type polarization by mediating c-MYC degradation." (PMID 35346215, 2022). "Interestingly, WNT4 expression in these cancers is accompanied by increased levels of FZD6 and MYC, i.e., features that we detected in aggressive TETs previously." (PMID 35965500, 2022). "In the case of oncogenic MYC, this mechanism promotes the acquisition of cancer hallmarks, such as non-adherent growth, and ultimately leads to cellular transformation." (PMID 36018850, 2022). "In particular, c-MYC and HIF-1α promote the expression of glycolytic enzymes hexokinase 2 (HK2), phosphofructokinase 1 (PFK1), triosephosphate isomerase 1 (TPI1), lactate dehydrogenase A (LDHA) in cancer." (PMID 36313705, 2022). "Similar to other cancers, KRAS and MYC are upstream activators of polyamine production in PDAC." (PMID 36551330, 2022). "Targeting oncogenic c-MYC and ODC1 has emerged as a strategy for cancer treatment." (PMID 36457036, 2022). "C-MYC is a cell cycle regulator located downstream of Wnt/β-Catenin, β-catenin accumulation in the nucleus can upregulate c-MYC, and increased c-MYC induces proliferation of cancer cells." (PMID 35053139, 2022).
cancer (continued). "The GSVA analysis of cancer hallmarks revealed that the high expression of BARX1 might trigger unfolded protein response, MYC target, and oxidative phosphorylation, and suppress apoptosis, IL6–JAK–STAT3 signaling, and inflammatory response." (PMID 36353226, 2022). "Given that MYC, SLC1A5, and mTORC1 levels are higher in glutamine-addicted cancer cells, along with glutaminase levels, all of these can be exploited in future clinical studies as biomarkers to identify patients when assessing the potential effectiveness of glutaminolysis inhibitors." (PMID 36499623, 2022). "CDK7 might also be an attractive target in MYC‐driven tumors: indeed, the covalent CDK7 inhibitor THZ1 disproportionally repressed super‐enhancer regulated genes, including MYC, MYCN and MYCL in diverse cancer‐derived cell lines." (PMID 36214609, 2022). "On the other hand, c-MYC-specific deubiquitinases can stabilize the c-MYC protein by rescuing it from degradation, making them attractive conceptual targets for the treatment of cancers." (PMID 35159073, 2022). "Moreover, some cancer-related pathways are also enriched in the C-score-identified buffering network, including the proto-oncogenes EGFR and MYC." (PMID 35194081, 2022). "UBE2C + cancer cells (Epi-C6) were mainly enriched in the following gene sets: MYC target V1, cell cycle, AKT and TGF-β signaling pathways and other gene sets; thus, these cells may promote the progression of cancer through these pathways." (PMID 36434043, 2022). "Therefore, the small molecule inhibitor 10058-F4, which blocks dimerization between MYC and MAX, was expected to be a breakthrough in targeting MYC-dependent cancer." (PMID 36611833, 2022). "Thus, we decided to study the expression of these two nuclear transcription factors involved in metabolic reprogramming of cancer cells and our data showed that resistant cells are characterized by higher levels of HIF-1α and lower levels of c-MYC." (PMID 35459212, 2022). "While these cells serve as an exquisite model to test the effect of oncogenic MYC, none of the known instances of MYC S146L in human cancer occur in tissues of the breast." (PMID 36018850, 2022). "LncRNA PVT1 promotes cancer initiation and progression by acting as a competing endogenous RNA (ceRNA), activating STAT3 signaling or KAT2A acetyltransferase, or interacting with myelocytomatosis oncogene (MYC)." (PMID 36713226, 2022). "However, treatment of another cancer cell line, HT1080, with both 0.16 and 0.08 μM sanguinarine reduced the level of c-MYC transcription to 71 and 65%, respectively." (PMID 36012470, 2022). "In fact, lack of correlation with MYC levels is not surprising, if we consider that cancer is more often dependent on tonic expression of MYC, rather than on its overexpression." (PMID 36860495, 2022). "A-485 suppresses p300-mediated histone acetylation and the transcription of key oncogenes such as MYC; and combination therapy with A-485 and JQ1 synergistically suppresses Wnt/β catenin pathway and c-Myc target gene expression, and synergistically induces NUT midline carcinoma cell apoptosis." (PMID 35836809, 2022). "While MYC is the main driver for these tumors, the amplification RRM2B and the other 8q-genes may be relevant for cancer cell survival, with therapeutic implications." (PMID 33868369, 2021).